XAF1 (XIAP associated factor 1)
Diseases named in the same sentence as XAF1 in open-access papers (continued):
Sharing a sentence is not in itself a finding about the gene and the disease.
neuroblastoma (continued). "Similarly, using KIF1Bβ homozygous-deleted NB1 neuroblastoma cell line, a decrease in cleaved caspase-3 levels upon ectopic expression of KIF1Bβ was also observed in the presence of XAF1 knockdown." (PMID 27097110, 2016). "Despite studies implicating XAF1 as a potential tumor suppressor in several cancers, the role of XAF1 in neuroblastoma tumor suppression remains unknown." (PMID 27097110, 2016). "Next, we asked whether XAF1 is required for KIF1Bβ-mediated apoptosis in neuroblastoma." (PMID 27097110, 2016). "Alternatively, we used a lentiviral approach to overexpress XAF1 in SK-N-SH and NLF neuroblastoma cells and similar results were obtained." (PMID 27097110, 2016). "In this study, we examined the expression of XAF1 in human neuroblastoma and found that XAF1 is either absent or lowly expressed in neuroblastomas." (PMID 27097110, 2016). "Our findings provide support that XAF1 and its functions such as XIAP inhibition may be a promising pathway to target for neuroblastoma treatment and management." (PMID 27097110, 2016).
ovarian carcinoma (3 papers, 2015 to 2022). A malignant neoplasm originating from the surface ovarian epithelium. "Recently, in vivo xenograft models of ovarian cancer have shown that the overexpression of XAF1 decreases the number of VM structures." (PMID 31612116, 2019). "However, our study shows the overexpression of XAF1 is positively correlated to epithelial phenotype and cisplatin resistance in ovarian cancer cell lines, indicating the phenotype‐dependent role of XAF1 in ovarian cancer cisplatin resistance." (PMID 35810383, 2022). "Therefore, XAF1 is a potent negative regulator of VM in ovarian cancer." (PMID 31612116, 2019).
pancreatic cancer (3 papers, 2014 to 2023). "XAF1 has been reported as a prognostic biomarker and therapeutic target for lung squamous cell carcinoma and pancreatic cancer." (PMID 36189255, 2022). "Our previous studies have shown that XAF1 is weakly expressed in human gastric, colon and pancreatic cancer tissues." (PMID 24980821, 2014). "Unlike the overexpression of XIAP in most human cancer tissues, XAF1 is ubiquitously expressed in normal and fetal tissues but weakly expressed or even undetectable in most human cancer cell lines and human cancer tissues including gastric, colon and pancreatic cancer." (PMID 24980821, 2014). "As we examined cell apoptosis in pancreatic cancer cells with or without AT-1976 treatment, we observed the same XAF1-dependent effect." (PMID 37189754, 2023).
Sepsis (3 papers, 2023 to 2026). Sepsis is defined as life-threatening organ dysfunction caused by a dysregulated host response to infection. "Prior scRNA‐seq findings revealed significant upregulation of ZBP1, XAF1, IFI44L and SOCS1 in B cells from sepsis patients that exhibit increased susceptibility to PANoptosis." (PMID 40600354, 2026). "Prior scRNA‐seq data showed pronounced upregulation of ZBP1, XAF1, IFI44L and SOCS1 in B cells from sepsis patients that displayed heightened PANoptosis sensitivity." (PMID 40600354, 2026). "Additionally, ZBP1, XAF1, IFI44L, SOCS1, and PARP14 were notably high in HighPANscore cells, aligning with our observations of upregulated expression of IFI44, IFIH1, IFIT1, IFIT2, and RSAD2 in lung tissues from sepsis-induced animal models." (PMID 38239341, 2023).
urogenital cancers (3 papers, 2007 to 2021). "Previous studies had indicated that loss of xaf1 expression, due at least in part to promoter methylation, is associated with increased tumor severity in gastric and urogenital cancers." (PMID 17376236, 2007).
brucellosis (2 papers, 2018 to 2024). Brucellosis is a bacterial infection that spreads from animals to people via unpasteurized dairy products or by exposure to contaminated animal products or infected animals. "The upregulated genes in granzyme/perforin, TNF, XAF1 and FAS apoptosis pathways may result in elevated apoptosis of CD8+ T cells in brucellosis patients and thus directly inhibit CD8+ T‐cell‐mediated responses." (PMID 39135683, 2024). "Further analysis found that granzyme/perforin, TNF, XAF1, and FAS apoptosis pathways might contribute to apoptosis of NK cells in patients with brucellosis, potentially exerting a direct inhibitory effect on NK cell‐mediated responses." (PMID 39135683, 2024).
lung adenocarcinoma (2 papers, 2014 to 2023). A carcinoma that arises from the lung and is characterized by the presence of malignant glandular epithelial cells. "The aim of this study is to investigate the effect and the mechanism of adenovirus vector Ad5/F35 mediated X-linked inhibitor of apoptosis protein associated factor-1 (XAF1) on the inhibition of cell proliferation and the induction of apoptosis of human lung adenocarcinoma cell A549." (PMID 25539606, 2014). "Restored XAF1 expression inhibits cell proliferation and induces cell apoptosis in human lung adenocarcinoma cell line A549." (PMID 25539606, 2014). "mRNA and protein expressions of XAF1 were significantly increased in human lung adenocarcinoma cell A549 after this cell was transfected with Ad5/F35-XAF1 for 48 h; these expressions were higher than those of the controlled group Ad5/F35-NULL." (PMID 25539606, 2014).
metastatic disease (2 papers, 2009 to 2021). "Our transcriptomic data analysis showed that high XAF1 mRNA expression both in primary and metastatic tumors was associated with better patient survival." (PMID 33734579, 2021). "Although the prognostic value of XAF1 in ccRCC appears to be limited, its predictive value remains to be determined, especially in patients with metastatic disease undergoing novel combination therapies of targeted agents with Interferon-alpha." (PMID 19664236, 2009).
renal carcinoma (2 papers, 2007 to 2009). A carcinoma arising from the epithelium of the renal parenchyma or the renal pelvis. "Low XAF1 tumour levels are also associated with a shortened overall survival of ccRCC patients but do not provide independent prognostic information when adjusting for standard pathological parameters for outcome prediction of renal cancer." (PMID 19664236, 2009).
sarcoidosis (2 papers, 2014 to 2019). Sarcoidosis is a multisystemic disorder of unknown cause characterized by the formation of immune granulomas in involved organs. "Regarding XAF1, XAF1 was one risk gene of sarcoidosis which implicated dysregulated immune responses." (PMID 31443559, 2019). "The SNP with the lowest p-value at the most significant novel admixture locus (17p13.3–13.1)—rs6502976—is located within intron 5 of the XAF1 gene, a novel candidate risk gene for sarcoidosis." (PMID 24663488, 2014). "The locus on chromosome 17p13.3–13.1 revealed a novel sarcoidosis risk SNP, rs6502976 (p = 9.5*10−6), within intron 5 of the gene X-linked Inhibitor of Apoptosis Associated Factor 1 (XAF1) that accounted for the majority of the admixture linkage signal." (PMID 24663488, 2014). "To further explore XAF1 as a novel sarcoidosis candidate susceptibility gene in African Americans, we conducted IHC protein expression studies for both the XAF1 and X-linked inhibitor of apoptosis (XIAP) genes in granulomatous sarcoidosis-affected tissue." (PMID 24663488, 2014). "Validation studies of our XAF1 association in independent samples as well as additional XAF1 functional studies are needed to further validate and define the role of this novel gene in sarcoidosis pathogenesis." (PMID 24663488, 2014). "Variation at the most promising novel sarcoidosis susceptibility gene, XAF1, may explain in part why African Americans are at increased risk for sarcoidosis." (PMID 24663488, 2014). "Results show suggestive evidence for SNP rs6502976 as an eQTL for XAF1 through linkage disequilibrium with two other SNPs (rs9891567 and rs1533031) that have been directly genotyped in studies of European individuals; both of these SNPs are also associated with risk of sarcoidosis." (PMID 24663488, 2014). "In conclusion, ancestry and association fine mapping revealed a novel sarcoidosis susceptibility gene, XAF1, which has not been identified by previous genome-wide association studies." (PMID 24663488, 2014). "XAF1 expression is present at the periphery of the specimen, in histologically normal cells distal to granulomas; increased XIAP staining (3e–f) clearly demarcates the sarcoidosis granulomas." (PMID 24663488, 2014). "Immunohistochemical expression studies demonstrated lack of expression of XAF1 and a corresponding high level of expression of its downstream target, X-linked Inhibitor of Apoptosis (XIAP) in sarcoidosis granulomas." (PMID 24663488, 2014). "In IHC expression studies, we observed lack of XAF1 expression in sarcoidosis affected tissues and higher XIAP expression within sarcoid granulomas than in surrounding tissues." (PMID 24663488, 2014). "XAF1 also antagonizes the cellular inhibitor of apoptosis genes C-IAP1 and C-IAP2, and may sensitize cells to Fas-mediated apoptosis, which is thought to play a role in sarcoidosis." (PMID 24663488, 2014). "Based on the known biology of the XIAP/XAF1 apoptosis pathway and the differential expression patterns of XAF1 and XIAP in sarcoidosis granulomas, we suggest that this pathway may play a role in the maintenance of sarcoidosis granulomas." (PMID 24663488, 2014). "Because XAF1 protein expression was low to absent in sarcoidosis-affected tissues, we hypothesize that any role rs6502976 plays in disease etiology would be early in pathogenesis, before sarcoidosis granulomas are histologically detectable." (PMID 24663488, 2014).
adenoma (1 paper, 2025). A neoplasm arising from the epithelium. "The study identified mutations in senescence-associated genes, namely, ATM, PIF1, TELO2, XAF1, and RBL1, in five of twenty subjects with multiple adenomas, indicating germline loss-of-function variants in genes that regulate senescence pathways with the development of serrated adenomas." (PMID 40699620, 2025).
astrocytomas (1 paper, 2020). "XAF1 expression correlated inversely with patient survival (similar to its prognostic role in IDH-mutant LGG); thus, XAF1 may have a unique, yet undescribed biologic function in astrocytomas." (PMID 32640746, 2020).
atherosclerosis (1 paper, 2022). A disease characterized by the build-up of fatty material and calcium deposition in the arterial wall resulting in partial or complete occlusion of the arterial lumen. "XAF1 (XIAP-associated factor 1) activates the mitochondrial apoptosis pathway and is used as a proapoptotic factor in treating cerebral ischemia–reperfusion injury, cancer prognosis, and atherosclerosis of the aorta." (PMID 36071497, 2022).
cerebral malaria (1 paper, 2025). A sequestration of Plasmodium falciparum in the brain, which can cause coma and/or seizures. "X-linked inhibitor of apoptosis-associated factor 1 (XAF1) was the most significant transcript uniquely associated with protection from concurrent cerebral malaria and severe malarial anemia." (PMID 40383794, 2025).
diabetes (1 paper, 2022). "Here, we generated transgenic mice selectively expressing the Xaf1 gene in β-cells, and examined the effects of β-cell XAF1 on β-cell function and the development of diabetes in vivo." (PMID 35829914, 2022). "Here, we explored the effects of XAF1 on β-cell function and progression of diabetes in vivo." (PMID 35829914, 2022). "Therefore, targeting excess XAF1 expression in pancreatic β-cells may provide a therapeutic objective to prevent β-cell depletion in diabetes." (PMID 35829914, 2022). "In conclusion, the present study clearly demonstrates that XAF1 expression in pancreatic β-cells via HFD-induced secretion of IFNβ from macrophages promoted β-cell apoptosis, thereby leading to a reduction in insulin secretion and exacerbation of diabetes." (PMID 35829914, 2022).
emphysema (1 paper, 2017). "In the Salmon model we saw that out of the top 10 kME genes, only one was significantly associated with emphysema at the α = 0.05 level, namely XAF1 (p = 0.037)." (PMID 29016655, 2017).
Impaired glucose tolerance (1 paper, 2022). An abnormal resistance to glucose, i.e., a reduction in the ability to maintain glucose levels in the blood stream within normal limits following oral or intravenous administration of glucose. "Furthermore, HFD-fed Xaf1 Tg mice demonstrated increased β-cell apoptosis, attenuated insulin expression, and impaired glucose tolerance compared with WT mice fed the same diet." (PMID 35829914, 2022). "Furthermore, HFD-fed Xaf1 Tg mice demonstrated increased β-cell apoptosis, lowered insulin expression, and impaired glucose tolerance compared with WT mice fed the same diet." (PMID 35829914, 2022).
liver fibrosis (1 paper, 2023). "Thus, further investigations are urgently needed to explore how inhibition of Xaf1, Slfn4, Slfn8, and Ifi213 by CVC can attenuate liver fibrosis." (PMID 37215993, 2023).
lymph node metastasis (1 paper, 2013). "The loss of XAF1 protein significantly correlated with H. pylori infection, tumor size, histological differentiation, lymphatic invasion, venous invasion, invasive depth, lymph node metastasis, distant metastasis and clinical stage (all p<0.05)." (PMID 23826230, 2013).
malignant glioma (1 paper, 2017). A grade III or grade IV glioma arising from the central nervous system. "Since the in vitro data in GB cells suggest an impact of XAF1 on the sensitivity to TMZ, we addressed the question whether XAF1 expression plays a role in the course of disease of malignant gliomas." (PMID 28122345, 2017).
microphthalmia (1 paper, 2024). Congenital or developmental anomaly in which the eyeballs are abnormally small. "Further upstream of the caspases in the apoptosis pathway, XAF1 (LFC +5.26, p < 0.0001), IRF1 (LFC +1.53, p < 0.000341), and STAT1 (LFC +1.850, p < 0.000000118) and pro-apoptotic genes BIRC3 (LFC +2.39, p < 0.00000695) and BIK (LFC +1.43, p < 0.00178) was upregulated in microphthalmia patients." (PMID 38821055, 2024).
neuroendocrine tumours (1 paper, 2022).
prion disease (1 paper, 2022). A transmissible disease that is caused by a protein that is able to induce abnormal folding of normal cellular proteins, leading to characteristic spongiform brain changes, which are associated with neuronal loss without an inflammatory response. "That study concluded lack of SARM1 led to an upregulation of the pro-apoptotic gene Xaf1, leading to an increase in neuronal apoptosis and shorter prion disease incubation times." (PMID 35507602, 2022). "Our data are not incompatible with an important role for increased expression of XAF1 in SARM1KO mice contributing to prion disease tempo." (PMID 35507602, 2022).
ZIKV infection (1 paper, 2020). "It is important to note that in our analysis, we identified two other DEGs not yet independently associated with ZIKV infection, to our knowledge: X- linked inhibitor of apoptosis protein associated factor 1 (XAF1) and tumor necrosis factor receptor superfamily member 1A (TNFRSF1)." (PMID 32079323, 2020). "We could not ascertain other studies showing XAF1 association with ZIKV infection." (PMID 32079323, 2020).
tumor (63 papers, 2006 to 2026). "XIAP-associated factor 1 (XAF1) is recognized as a potential tumor suppressor, and XAF1 has been scrutinized for its role in cancer progression, particularly in gastric and colon malignancies." (PMID 40718833, 2025). "Epigenetic inactivation of XAF1 is observed in various types of human cell lines and primary tumor tissues and associated with the malignant progression of multiple tumors." (PMID 39532800, 2024). "It exists at a remarkably high frequency in the population of southeast Brazil as founder mutation in two distinct haplotypes with the most frequent co-segregating with the p.E134∗ variant of the XAF1 tumor suppressor and an increased cancer risk." (PMID 37794678, 2024). "In the current study, we observed that TRIM28 elevation is associated with abnormal reduction of XAF1 in cancer cell lines and tumor tissues." (PMID 39532800, 2024). "X-linked inhibitor of apoptosis (XIAP)-associated factor 1 (XAF1) is a pro-apoptotic tumor suppressor that is originally found to antagonize the anti-caspase activity of XIAP." (PMID 35902580, 2022). "The X-linked inhibitor of apoptosis (XIAP)-associated factor 1 (XAF1), also found in Omy27, is a regulator of cytokinesis that considerably increases stress-induced apoptosis and decreases the invasive capacity of tumor cells." (PMID 36672855, 2022). "Meanwhile, we observed that ATM is activated by TMZ in both resistant and sensitive tumor cells, and XAF1 induction causes further activation of ATM, which is required for TMZ-induced apoptosis." (PMID 35274103, 2022). "XAF1 (XIAP Associated Factor 1) functions as a tumor suppressor by mediating apoptosis stress response of cancer cells." (PMID 35719970, 2022). "X-linked inhibitor of apoptosis-associated factor 1 (XAF1) is a tumor suppressor that is commonly inactivated in multiple human cancers." (PMID 35274103, 2022). "X-linked inhibitor of apoptosis-associated factor-1 (XAF1) is a stress-inducible tumor suppressor that is commonly inactivated in many human cancers." (PMID 35902580, 2022). "For instance, epigenetic regulation of XIAP associated factor 1 (XAF1), a previously reported tumor suppressor was recently reported to mediate plasticity towards adaptive resistance in GBM to TMZ." (PMID 34361090, 2021). "X-linked inhibitor of apoptosis (XIAP)-associated factor 1 (XAF1) is a proapoptotic tumor suppressor whose expression is commonly inactivated in a broad range of human malignancies mainly by aberrant promoter hypermethyaltion." (PMID 30042418, 2018). "X-linked inhibitor of apoptosis (XIAP)-associated factor 1 (XAF1) is a proapoptotic tumor suppressor that is frequently inactivated in multiple human cancers." (PMID 30042418, 2018). "XAF1 (X-linked inhibitor of apoptosis (XIAP)-associated factor 1) is a tumor suppressor that counteracts the anti-apoptotic effects of XIAP and can sensitize cells to cell death triggering events." (PMID 28122345, 2017). "The loss of XAF1 expression will render tumor cells resistance to apoptosis and promote tumor cell survival." (PMID 23826230, 2013). "Corresponding to the observed associations of low XAF1 protein expression with advanced tumour stages and grades, we found low XAF1 tumour levels to predict an impaired prognosis in univariate, but not in multivariable analyses." (PMID 19664236, 2009). "Low XAF1 expression in ccRCC tissue, however, was associated with progression of tumour stage (p = 0.040) and grade (p < 0.001)." (PMID 19664236, 2009). "Conversely, transcriptional down-regulation of XAF1 expression has been reported to occur in RCC and low XAF1 mRNA tumour levels have also been linked to impaired prognosis in RCC patients." (PMID 19664236, 2009). "XIAP-associated factor 1 (XAF1) is a putative tumor suppressor that exerts its proapoptotic effects through both caspase-dependent and – independent means." (PMID 17376236, 2007). "Next, we asked whether XAF1 tumor suppression function is linked to the TRIM28-destabilizing activity." (PMID 39532800, 2024).